P2RX6P (purinergic receptor P2X 6 pseudogene)
Gene: Transcribed unprocessed pseudogene on chromosome 22 (21,042,343 to 21,045,017, reverse strand). Ensembl gene ENSG00000206145.
Diseases named in the same sentence as P2RX6P in open-access papers:
P2RX6P is named in the same sentence as 1 disease in open-access papers, as found by Europe PMC text mining. Sharing a sentence is not in itself a finding about the gene and the disease.
P2RX6P shares sentences with these, for which no sentence is quoted: morbid obesity (1 paper).